PRL (prolactin)
Diseases named in the same sentence as PRL in open-access papers (continued):
Sharing a sentence is not in itself a finding about the gene and the disease.
Arthritis (7 papers, 2015 to 2025). Inflammation of a joint. "Prolactin protects against inflammation-associated chondrocyte apoptosis in arthritis." (PMID 29367664, 2018). "Upregulation of vasoinhibin can contribute to the beneficial outcome of PRL in arthritis by means of its inhibitory effects on blood vessels." (PMID 35721729, 2022). "Experimental studies showed that increasing prolactinemia, either by PRL infusion or treatment with the dopamine D2 receptor blocker haloperidol, ameliorates the severity of arthritis, either directly or via the PRL conversion to antiangiogenic vasoinhibin." (PMID 35721729, 2022). "PRL signals directly on chondrocytes and synovial fibroblasts to inhibit cartilage degradation, synovial inflammation, and osteoclastogenesis in arthritis." (PMID 35721729, 2022). "Major questions are how and when PRL and vasoinhibin opposing actions operate and mechanistically interact to influence arthritis progression." (PMID 35721729, 2022). "It remains to be determined how PRL actions, particularly the downregulation of T regulatory cells, would contribute to PRL protection against inflammation and osteoclastogenesis in arthritis." (PMID 28506283, 2017). "Further supporting a role for PRL in arthritis pathogenesis, the dopamine agonist bromocriptine reduces systemic PRL production and has beneficial effects in patients with RA and in animal models of disease." (PMID 25717285, 2015). "However, murine inflammatory arthritis has been extensively used for drug development and has provided insights into the influence of the PRL/vasoinhibin axis on joint inflammation." (PMID 35721729, 2022). "The positive role of PRL in murine arthritis contrasts with its controversial action in RA." (PMID 35721729, 2022). "PRL infusion in AIA was associated with reduced serum levels of C-reactive protein (CRP) and TNFα, two biomarkers of systemic inflammation in arthritis." (PMID 28506283, 2017). "Locally produced PRL has both pro-inflammatory and anti-inflammatory effects in arthritis." (PMID 28690611, 2017). "Supporting the anti-inflammatory role of PRL in arthritis, PRL-receptor-null mice exhibited increased joint swelling and higher joint expression of the genes encoding for TNFα, IL-1β, IL-6, IFNγ, IL-17A, IL-21, IL-22, IL-23, and IL-10 when subjected to monoarticular AIA (MAIA)." (PMID 28506283, 2017). "We found that there were significant correlations between patient age, pregnancy weeks, numbers of delivery, and levels of PRL (P<0.05), but also between levels of ESR and CRP, erythema nodosum and arthritis (P<0.05)." (PMID 41001015, 2025). "Recombinant PRL regulates gene expression pathways that control inflammation, proliferation, and cell survival in synoviocytes, suggesting that NR4A2-induced PRL may elicit similar autocrine responses that may subsequently impact arthritis progression." (PMID 25717285, 2015). "In synoviocytes, recombinant PRL regulates several genes involved in inflammation, proliferation, and cell survival, suggesting that NR4A2 induced PRL may also impact these pathways and contribute to arthritis progression." (PMID 25717285, 2015).
Azoospermia (7 papers, 2020 to 2025). Absence of any measurable level of sperm,whereby spermatozoa cannot be observed even after centrifugation of the semen pellet. "Generally, hormonal analysis has shown that prolactin was slightly higher than the normal level in azoospermia participants with microdeletion, 56.3% of Azoospermic have higher prolactin levels compared to 14.3% in the Oligozoospermic." (PMID 33892694, 2021). "Generally, hormonal analysis in our study has shown that prolactin was slightly higher than the normal level in azoospermia participants with microdeletion." (PMID 33892694, 2021). "Hyperprolactinemia, or elevated serum prolactin levels, is a rare etiology for azoospermia but clinically relevant." (PMID 33807489, 2021). "Semen analysis confirmed total azoospermia along with an unaffected hormonal profile for serum follicle stimulating hormone (FSH), luteinizing hormone (LH), and prolactin levels." (PMID 32490605, 2020).
cytomegalovirus infection (7 papers, 2020 to 2025). A herpesvirus infection caused by Cytomegalovirus. "The prolactin receptor (PRLR) and human cytomegalovirus (HCMV) proteins are frequently detected in ovarian tumor tissue specimens, but the potential impact of HCMV infection on the PRL system have so far not been investigated." (PMID 32121009, 2020).
eating disorder (7 papers, 2016 to 2025). A broad group of psychological disorders with abnormal eating behaviors leading to physiological effects from overeating or insufficient food intake. "In the univariable binary logistic regression models, BMI, excessive exercise and eating disorders were associated with prolactin levels < 12 μg/L." (PMID 37957366, 2024). "Eating disorders and excessive exercise where associated with prolactin levels < 12 μg/L, in contrast to TSH." (PMID 37957366, 2024). "Overall, it appears that metabolic causes like excessive exercise, eating disorder and BMI were predominantly influencing prolactin levels in this population of FHA women, even though BMI was only a significant parameter in the univariable model." (PMID 37957366, 2024). "In the univariable model, the causes of FHA were of major influence, where stress significantly increased the risk for a higher prolactin (OR 4.321, p < 0.001), whereas underweight, eating disorders and excessive exercise decreased the risk (p < 0.050)." (PMID 37957366, 2024). "Eating disorders and excessive exercise tend to lower prolactin levels in FHA women, whereas TSH is associated with prolactin levels > 12 μg/L." (PMID 37957366, 2024). "By our study group, eating disorders and excessive exercise tended to lower prolactin levels in FHA women." (PMID 38592037, 2024). "In a multivariable binary logistic regression model eating disorder (odds ratio, OR 0.206; p = 0.040), excessive exercise (OR 0.280; p = 0.031) and TSH (OR 1.923; p = 0.020) were significantly associated with prolactin levels > 12 μg/L." (PMID 37957366, 2024). "It is also important to note that susceptibility to eating disorders (DEAs) may influence HPA axis function and the levels of hormones such as prolactin and cortisol." (PMID 40218947, 2025). "Eating disorders, which are associated with decreased calorie intake, as well as excessive exercise were associated with prolactin levels < 12 μg/L, whereas higher TSH levels were linked to higher prolactin levels in women with FHA." (PMID 37957366, 2024).
Gonadotropin deficiency (7 papers, 2015 to 2025). A reduced ability to secrete gonadotropins, which are protein hormones secreted by gonadotrope cells of the anterior pituitary gland, including the hormones follitropin (FSH) and luteinizing hormone (LH). "All prolactin-deficient patients also had severe GH deficiency, gonadotropin deficiency, and central hypothyroidism." (PMID 39356415, 2024). "Thyrotropin and gonadotropin deficiencies were also very frequent at presentation, and low prolactin was reported in 60%." (PMID 39356415, 2024). "The only statistically significant finding was the observation that GH(+)/PRL(+) tumors presented a higher PRL concentration and higher rate of gonadotropin deficiency, which complies with the common endocrine knowledge." (PMID 38137536, 2023). "Patients with GH(+)/PRL(+) had a significantly higher PRL concentration and more common gonadotropin deficiency in comparison to patients with pure GH(+) and plurihormonal tumors." (PMID 38137536, 2023). "Elevated prolactin was the most common finding (90%), followed by gonadotropin deficiency (82%), ACTH deficiency (70%), and TSH deficiency (60%)." (PMID 27651959, 2016). "To date, mutations in PROP1 are associated with growth hormone (GH), thyrotropin (TSH), prolactin (PRL) and gonadotropin deficiencies." (PMID 25434367, 2015). "For instance, patients homozygous for the p.R120C mutation may first present in childhood with GHD before the later development of TSH, prolactin and gonadotropin deficiencies." (PMID 26416826, 2015). "Recessive PROP1 mutations are associated with GH, TSH, prolactin and gonadotropin deficiency, although the timing and extent of these deficits vary and the full phenotype may not be evident from the outset." (PMID 26416826, 2015). "Furthermore, multivariable analyses demonstrated that high baseline PRL values (HR 23.9, 95% CI 1.0-593.7, p = 0.05), rather than the prevalence of headaches at diagnosis or gonadotropin deficiency, were independent risk factors for persistent DA dependence in the long term." (PMID 39904877, 2025).
gynecological cancers (7 papers, 2004 to 2025). "More recently, various hypotheses have been put forth to explain a potential association between antidepressants and gynecologic cancer risk, including increased release of gonadotropins and prolactin as well as induced apoptosis of cancer cells." (PMID 40427115, 2025). "Prolactin (PRL) acts through a series of receptors (PRLRs), and its effects on gynecological cancers include migration, invasion, metastasis, inhibition of apoptosis, and chemoresistance." (PMID 38543693, 2024). "In gynecologic cancers, PRL exhibits antiapoptotic and pro-tumoral properties by promoting tumor cell migration, invasion, metastasis, and chemoresistance via various signaling pathways and effector proteins." (PMID 35406551, 2022). "Because women produce high levels of PRL, its influence in gynecological cancers is herein reviewed." (PMID 34745013, 2021). "In this review, we analyze these findings, and we present the current panorama of research on PRL-PRLR and its effects on gynecological cancers and the perspectives on the use of PRL as a therapeutic target." (PMID 34745013, 2021). "Due to the pro- and anti-tumor evidence of PRL existing in the literature, in this review we delve into this topic to provide an overview and understand the role of PRL in gynecological cancers." (PMID 34745013, 2021). "Numerous reports show evidence of the effect of PRL-PRLR promoting cellular malignant characteristics in gynecological cancers, and there are even a few reports suggesting a possible anti-tumor effect generated by this ligand-receptor binding." (PMID 34745013, 2021).
hyperlipidemia (7 papers, 2006 to 2024). "Increased hyperlipidemia could be caused by a combination of IR associated with hormonal changes, such as decreased progesterone, prolactin and estradiol." (PMID 26633694, 2015).
inflammatory bowel disease (7 papers, 2018 to 2025). A spectrum of small and large bowel inflammatory diseases of unknown etiology. "The top 5 KEGG pathways were Inflammatory bowel disease, Antifolate resistance, Apoptosis-multiple species, Adipocytokine signaling pathway, Prolactin signaling pathway." (PMID 37698530, 2023). "The enriched pathway was the Jak-STAT signaling pathway, focal adhesion, inflammatory bowel disease, regulation of actin cytoskeleton, adherens junction, and prolactin signaling pathway for the DEGs in the turquoise module." (PMID 29443735, 2018).
iron deficiency (7 papers, 2017 to 2025). "Iron deficiency affects prolactin levels as prolactin is a peripheral marker of central dopamine release." (PMID 36231287, 2022). "Notably, iron deficiency has been associated with elevated serum prolactin levels and subsequent dopaminergic neuron defects." (PMID 39201626, 2024). "As prolactin is a stress hormone and the secretion of prolactin often acts to maintain homeostasis, it is important to elucidate whether such elevation of prolactin in response to iron deficiency provides any feedback or tolerance to cells." (PMID 39201626, 2024). "Interestingly, prolactin elevation is noted in patients with iron deficiency." (PMID 39201626, 2024).
liver cirrhosis (7 papers, 2013 to 2025). "A serum PRL cutoff value of 50 ng/mL has been identified as a predictor of mortality for individuals with liver cirrhosis, particularly those experiencing hepatic encephalopathy." (PMID 41476991, 2025). "Ayfer reported that individuals with alcoholic and HBV‐related liver cirrhosis exhibited lower serum testosterone levels alongside elevated estradiol and PRL levels when compared to a control group." (PMID 41476991, 2025). "This compensatory role is further supported by observations that prolactin levels increase proportionally with the severity of liver cirrhosis." (PMID 40964426, 2025). "Decreased serum testosterone level and increased estradiol and prolactin levels were observed in both groups with alcoholic and HBV-related liver cirrhosis, compared to the control group." (PMID 27785243, 2013). "However, they observed that patients with liver cirrhosis exhibited significantly higher serum PRL levels, even in the absence of hepatic encephalopathy." (PMID 41476991, 2025).
multiple endocrine neoplasia type 1 (7 papers, 2019 to 2025). An autosomal dominant tumor predisposition syndrome caused by pathogenic variants in the MEN1 gene, characterized by an increased risk of tumors of the parathyroid glands, pituitary gland, and foregut neuroendocrine tumors (most commonly pancreatic islet cells). "Despite the predominance of macroadenoma documented in multiple endocrine neoplasia type 1 (MEN1)-related prolactinoma, only three giant prolactinoma cases were described so far (size > 40 mm and prolactin > 1,000 ng/mL)." (PMID 31555208, 2019). "In terms of multiple endocrine neoplasia type 1 (MEN-1) screening, anterior pituitary function, including levels of sex hormones, prolactin, growth hormone, thyroid-stimulating hormone (TSH), thyroid function, adrenocorticotropic hormone (ACTH) and cortisol, was not obviously abnormal." (PMID 31852474, 2019). "Prolactin, parathyroid hormone (PTH), albumin, and calcium levels, as well as MRI of his brain were normal, ruling out multiple endocrine neoplasia type 1 (MEN-1)." (PMID 31234935, 2019).
osteoarthritis (7 papers, 2016 to 2022). A noninflammatory degenerative joint disease occurring chiefly in older persons, characterized by degeneration of the articular cartilage, hypertrophy of bone at the margins and changes in the synovial membrane. "In the doxorubicin-only treatment group, genes in the prolactin signaling pathway, the allergic inflammatory airway disease pathway by IL-17F, the Wnt/Ca2+ pathway, and the osteoarthritis pathway demonstrated significant gene expression changes." (PMID 33801927, 2021). "The purpose of our study was the assessment of the effect of spa therapy, consisting of peloid therapy, physical therapy, kinesiotherapy, and radon water, on changes in concentration of TAS, CRP, and PRL in patients with osteoarthritis." (PMID 32373171, 2020). "The main purpose of our study was the assessment of the effect of spa treatment on changes in concentration of TAS, CRP, and PRL in patients with osteoarthritis." (PMID 32373171, 2020). "PRL levels in plasma and synovial fluid (SF) of patients with RA and osteoarthritis (OA) have been reported to be comparable, but the potential relationship between PRL levels in blood and SF has only recently been studied." (PMID 28690611, 2017). "In the context of the prolactin role in patients with osteoarthritis, a decrease rather than an increase in the level of this hormone, of course within the reference range, seems beneficial." (PMID 32373171, 2020).
postpartum depression (7 papers, 2016 to 2025). A type of clinical depression that occurs after childbirth. "Reduced PRL concentrations in lactating women have been associated with an increased risk of developing postpartum depression." (PMID 40565372, 2025). "The aspect of postpartum depression, which is also associated with high PRL levels resulting from lactation, is also important." (PMID 36833950, 2023). "However, no alterations out of the physiological range were found for prolactin, oxytocin, or vasopressin associated with postpartum depression." (PMID 26819762, 2016). "Low PRL levels in nursing women have been associated with postpartum depression." (PMID 27065946, 2016). "Timely SSC promotes oxytocin and prolactin production and lessens postpartum post-traumatic stress symptoms and postpartum depression (PPD) symptoms." (PMID 38397344, 2024). "It has been shown that in postpartum depression patients, increased regional grey mater volumes in the right anterior insula were positively correlated with PRL levels." (PMID 36833950, 2023). "The orchestration of emotional bonds relies on the interplay of oxytocin and prolactin, fundamental hormones that underpin maternal attachment, mitigate postpartum depression, and cultivate self-confidence." (PMID 38021634, 2023). "Interestingly, a study from 2022 reported contradictory results, claiming that patients with postpartum depression exhibited significantly higher serum PRL concentrations compared to healthy postpartum women." (PMID 40565372, 2025). "Administration of bromocriptine in the early stages of pregnancy reduces PRL levels, induces a depressive-like state, and impairs maternal behavior in female rats, suggesting that PRL may play a key role in the onset of postpartum depression." (PMID 27065946, 2016). "The contribution of PRL to the onset of postpartum depression is still unknown." (PMID 27065946, 2016). "Postpartum depression (PPD) affects approximately 10% of women and is closely related to endogenous hormonal secretion, and although it has been postulated to be related to estrogen, thyroxine, or autoimmune thyroid dysfunction, its strongest correlation is with high PRL and low progesterone levels." (PMID 36833950, 2023).
thyroid autoimmunity (7 papers, 2015 to 2025). "In the present study, we aimed to assess the contribution of macroprolactin to high serum prolactin levels and the association of prolactin (PRL) and macroprolactin (macroPRL) levels with thyroid status and thyroid autoimmunity during pregnancy." (PMID 26091810, 2015). "Thus, attenuation of the prolactin-lowering effect of metformin was likely associated with thyroid autoimmunity." (PMID 39204081, 2024). "The results allow us to conclude that autoimmune thyroiditis mitigates the impact of metformin on prolactin secretion in men." (PMID 39204081, 2024). "In addition to the association with testosterone deficiency, particularly in individuals with markedly elevated prolactin levels; increased prolactin production may predispose to the development and progression of autoimmune disorders, including autoimmune thyroiditis." (PMID 39204081, 2024). "A neutral effect on thyroid antibody titers indicates that the weak effects of metformin on prolactin levels in patients with autoimmune thyroiditis cannot be explained by a direct involvement of these antibodies." (PMID 39204081, 2024). "Thus, it seems that the optimal treatment of patients with both these disorders should be directed at reducing both prolactin oversecretion and thyroid autoimmunity." (PMID 39852352, 2025). "The current study was aimed at investigating whether autoimmune thyroiditis modulates the impact of metformin on the plasma prolactin concentration in men." (PMID 39204081, 2024). "Increased prolactin production may contribute to the development and perpetuation of several autoimmune diseases, including autoimmune thyroid disease." (PMID 37297964, 2023). "In addition to thyroid autoimmunity and hypofunction of the hypothalamic–pituitary–thyroid axis, impaired sexual functioning may be partially explained by a decrease in testosterone and an increase in prolactin levels." (PMID 40428279, 2025). "Therefore, the current study was aimed at investigating whether thyroid autoimmunity modulates the impact of metformin on circulating levels of prolactin, other anterior pituitary hormones and their downstream hormones in young women with prolactin excess." (PMID 37297964, 2023). "Unlike other auto immune diseases, we could not find any relationship between thyroid autoimmunity and PRL, macroPRL or monoPRL %." (PMID 26091810, 2015).